PAX8 (paired box 8)
Diseases named in the same sentence as PAX8 in open-access papers (continued):
Sharing a sentence is not in itself a finding about the gene and the disease.
breast carcinoma (24 papers, 2009 to 2025). "Nuclear PAX-8 staining is useful for distinguishing between gynecologic cancers and other malignancies, such as malignant mesotheliomas and breast cancer with similar histologic features." (PMID 29433539, 2018). "PAX8 has been recently reported as a useful marker for the differentiation between ovarian and metastasized breast carcinoma." (PMID 19426511, 2009). "However, the scientific literature evidenced the presence of PAX-8 as a marker of distant metastasis of breast cancer, including secretory histologic types." (PMID 40391352, 2025). "The pathology of the thyroid samples disclosed a secondary malignancy of poorly differentiated breast cancer with immunophenotypes CK7+, CK 20-, GATA3+, TTF-1-, P40-, S100-, CDX-2-, Thyroglobulin-, Pax8-, and P63-." (PMID 37048792, 2023). "A previous study using microarray analysis revealed that PAX8 and EPAC are expressed at higher levels in ovarian compared with breast cancer." (PMID 23425942, 2013). "Metastatic breast carcinoma cells typically exhibit positive expression of mammary epithelial differentiation markers (e.g., GATA, Mammaglobin, ER/PR, TRPS1) and negative expression of thyroid follicular cell markers (e.g., Thyroglobulin, TTF-1, PAX-8)." (PMID 41199830, 2025). "Metastatic thyroid carcinoma (papillary, follicular, or medullary) can resemble papillary or apocrine breast lesions; however, TTF-1 (SPT24 clone) and PAX8 positivity support thyroid origin, while breast carcinomas are typically negative." (PMID 41510417, 2025). "In this patient, immunochemical staining was negative for PAX8, p40, ER, and PgR, ruling out thymic carcinoma and breast cancer metastasis." (PMID 38627639, 2024). "In this analysis, we used organ-specific antibodies, including TTF-1 for lung cancer, WT-1 or PAX8 for gynecological cancers, mammaglobin or GCDFP-15 for breast cancer, PSA for prostate cancer, CDX2 for gastrointestinal cancers, and uroplakin for urothelial cancers." (PMID 22299055, 2012). "The presence of PAX-8 is not known as a marker of distant metastasis of breast cancer." (PMID 40391352, 2025). "Important tumors with near complete absence of PAX8 staining (< 1%) included all subtypes of breast cancers, hepatocellular carcinomas, gastric, prostatic, pancreatic, and pulmonary adenocarcinomas, neuroendocrine neoplasms, small cell carcinomas of various sites, and lymphomas." (PMID 39105782, 2024). "Studies have also shown that PAX8 is not expressed in mammary carcinomas." (PMID 33504059, 2021). "No anti-PAX8 staining was observed in primary breast carcinoma (data not shown)." (PMID 20492709, 2010). "One study discovered that PAX8 (ENSG00000125618) is the best discriminatory marker between ovarian and breast carcinomas." (PMID 34917619, 2021).
congenital hypothyroidism (24 papers, 2009 to 2026). A thyroid hormone deficiency present from birth. "Heterozygous missense mutations localized to the PAX8 paired domain are capable of causing congenital hypothyroidism, and it has been demonstrated that the L62R mutation in the paired domain leads to a reduction in PAX8 DNA binding." (PMID 38473380, 2024). "We aim to identify and characterize PAX8 mutations in a large cohort of congenital hypothyroidism(CH) from thyroid dysgenesis in Chinese population." (PMID 28060725, 2017). "Loss-of-function mutations of the PAX8 gene are considered to mainly cause congenital hypothyroidism (CH) due to thyroid hypoplasia." (PMID 21048839, 2009). "Interestingly, in at least one case, congenital hypothyroidism caused by a PAX8 mutation was also associated with unilateral kidney agenesis, highlighting the role that this gene also plays in renal development." (PMID 38473380, 2024). "Multiple families with deleterious PAX8 mutations have been described with congenital genitourinary anomalies including hydrocele, horseshoe kidney, cryptorchidism, and renal agenesis in the context of congenital hypothyroidism." (PMID 39639036, 2024). "Interestingly, pathogenic variants in TSHR and PAX8 genes have been reported in patients with permanent congenital hypothyroidism showing reduced to normal-sized eutopic thyroid glands with low to absent radioiodide uptake on thyroid scintigraphy." (PMID 35600585, 2022). "Mutations in the PAX8 gene in humans have been associated with congenital hypothyroidism." (PMID 26030152, 2015). "In humans, patients carrying mutations in the Pax8 gene suffer from congenital hypothyroidism." (PMID 25270402, 2014). "Interestingly, mutations in the Pax8 gene have been associated with congenital hypothyroidism in humans." (PMID 25270402, 2014). "The aim of the study was to investigate the impact of congenital hypothyroidism on currents through voltage-gated Na+ and potassium channels as well as expression of Na+/K+-ATPase isoforms in the hippocampus of Pax8−/− mice." (PMID 35456949, 2022). "PAX8 is also critical for the development of the thyroid gland; microdeletion of 2q12.1q14.1, involving PAX8, was described in a patient with congenital hypothyroidism, due to thyroid gland hypoplasia." (PMID 34768925, 2021). "For example, one proband had two pathogenic de novo variants in genes linked with two distinct conditions, resulting in seven phenotypes attributable to HDAC8 (Cornelia de Lange syndrome [MIM: 300882]) and just one attributable to PAX8 (congenital hypothyroidism [MIM: 218700])." (PMID 39353430, 2024). "Since acutely dissociated hippocampal neurons from Pax8−/− mice exhibited significantly smaller Na+ currents compared with wild-type and Pax8+/− mice, we investigated whether Na+/K+-ATPase expression is also influenced by congenital hypothyroidism." (PMID 35456949, 2022). "Similarly, Pax8 knockout mice exhibit a total lack of TFCs and some cases of congenital hypothyroidism in humans are found to be associated with PAX8 mutations." (PMID 24995001, 2014). "Considering that the Pax8−/− mouse does not have thyroid hormone-producing follicular cells, it acts as a suitable animal model to study the consequences of congenital hypothyroidism." (PMID 35456949, 2022). "Loss of function mutations in TSHR, PAX8, NKX2.1, NKX2.5 and FOXE1 genes are responsible for some forms of inherited congenital hypothyroidism, with or without hypoplastic thyroid." (PMID 25146893, 2014).
hypothyroidism (23 papers, 2009 to 2025). Abnormally low levels of thyroid hormone. "In order to further characterize the metabolic alterations associated with mild hypothyroidism in adult Pax8 +/- mice, we assessed several physiological parameters." (PMID 31518338, 2019). "Our study also substantiates that patients bearing PAX8 mutations resulting in mild hypothyroidism, are prone to develop diabetes (type 2 and gestational), as evidenced by our previous study, and likely to develop liver cancer." (PMID 31518338, 2019). "Herein, we show, using wild-type and the Pax8 ablated model of hypothyroidism in mice, that hyperthyroidism and severe hypothyroidism are associated with an overall unhealthy status and shorter lifespan." (PMID 31518338, 2019). "In mouse, stronger effects were related to earlier exposure or specific genetic background such as either Pax8 or Nkx2-1 haploinsufficiency, both associated to hypothyroidism in humans." (PMID 30397221, 2018). "Heterozygous mutations of thyroid enriched master regulators, such as Pax8 and Nkx2-1, have been associated to different grades of human hypothyroidism." (PMID 30397221, 2018). "Dgcr8 fl/fl; Pax8Cre+ knockout mice died prematurely, developed massive hypothyroidism and end stage renal disease due to a loss of miRNAs in Pax8 expressing tissue." (PMID 27090781, 2016). "A recent study has associated a novel PAX8 mutation with a severe form of hypothyroidism and abnormalities in the urogenital tract." (PMID 25484916, 2014). "Congenital hypothyroidism is caused by several genetic defects and among these there are mutations in the PAX8 gene." (PMID 21966443, 2011). "PAX8 regulates multiple genes involved in the production of thyroid hormone, an interesting result considering that both somatomotor and frontoparietal network-FC have been linked to (subclinical) hypothyroidism." (PMID 36882310, 2023). "If such a mechanism underlies the development of coma and death in severe hypothyroidism, Pax8−/− mice should show deficits in the expression of Na+ currents and potentially also in the expression of Na+/K+-ATPases, which are necessary to maintain low intracellular Na+ levels." (PMID 35456949, 2022). "As these mutations are also linked to hypothyroidism, we determined whether glucose metabolism was affected in adult (~7-month old) male Pax8 mice and whether T4 treatment could alleviate symptoms." (PMID 31518338, 2019). "Therefore, we propose the Pax8 +/- mouse as a valuable experimental model to further dissect the cellular and molecular mechanisms associated with mild hypothyroidism and hypothyroidism-related pathologies." (PMID 31518338, 2019). "Indeed, the TCDD exposure was worsened in genetic context characterized by haploinsufficiency of Pax8+/− or Nkx2-1+/−, genetic conditions, associated with hypothyroidism in humans." (PMID 30397221, 2018). "The second group displayed a severe phenotype comparable to that observed in age-matched Pax8(Cre/+); Dicerflox/flox mice, with hypothyroidism associated with low T4 plasma levels (0, 47±0, 386 μg/dl), disruption of thyroid architecture and post-weaning lethality." (PMID 22242190, 2012). "Indeed, among the putative MEs we identified are genes implicated in hypothyroidism (PAX8), and Tourette's syndrome (SLITRK1)." (PMID 21203497, 2010). "Our experiments were performed in hippocampal tissue from Pax8−/− mice serving as a suitable animal model for extreme hypothyroidism." (PMID 35456949, 2022). "In order to determine the effect of lower levels of THs in mouse healthspan and lifespan, we used the murine Pax8 model of hypothyroidism." (PMID 31518338, 2019). "Nkx2-1 and Pax8 double heterozygous mice of 129/Sv genetic background display thyroid hemiagenesis and hypothyroidism, indicating a polygenic origin of the thyroid hemiagenesis." (PMID 31465501, 2019). "Considering the hypothyroidism phenotype present only in Nkx2‐1−/− or Pax8−/− or double Nkx2‐1+/−Pax8+/− mice, we decided to study directly the knock‐out mice." (PMID 30446499, 2018).
hypothyroidism (continued). "Pax8-/- mice, in which hypothyroidism only manifests itself postnatally, show normally developed retinal layers and normal cell morphologies; their only known retinal abnormality is in cone opsin expression." (PMID 27942035, 2016). "Nevertheless, at three weeks of age, Pax8-cDicer (−/−) mutant mice showed growth retardation, displayed profound hypothyroidism with low total T4 (0,248±0,126 μg/dl representing Mean±S.D)." (PMID 22242190, 2012). "Inducible Pax8-Cre–mediated deletion of GRP170 triggers hypothyroidism." (PMID 40923318, 2025). "Contrary to other experimental models of hypothyroidism, PAX8 heterozygous mice realistically reflect the human hypothyroid phenotype, including insulin resistance, increased white adipose tissue mass, and increased triglyceride content in the skeletal muscle and liver." (PMID 37600699, 2023). "Direct regulation of TH levels using PAX8 heterozygous knockout mice, which suffered mild hypothyroidism due to direct thyroid defects but exhibited normal circulating levels of pituitary hormone alpha-GSU in adulthood, did not result in improved healthy lifespan or longer lifespan." (PMID 37600699, 2023). "They evidence a functional DNA-binding impairment, suggesting that hypothyroidism could be secondary to PAX8 haploinsufficiency." (PMID 25146893, 2014). "In addition to hypothyroidism, PAX8 plays a role in the progression of follicular thyroid carcinomas and adenomas and is overexpressed in the majority of gliomas, Wilms tumors and well-differentiated pancreatic neuroendocrine tumors." (PMID 24766781, 2014). "Although site directed loss-of-function mutants have been reported in hypothyroidism, no gain-of-function mutants have been reported for PAX8 in any cancers." (PMID 24628993, 2014). "Most of Pax8(Cre/+); Dicerflox/flox mice usually die around weaning time due to hypothyroidism." (PMID 22242190, 2012). "In addition to hypothyroidism, PAX8 plays a role also in the progression of follicular thyroid carcinomas and adenomas." (PMID 21966443, 2011). "Additionally, PAX8 heterozygous mice performed poorly in functional physical tests with accumulation of oxidative damage, suggesting that even minor alterations in TH levels (mild hypothyroidism) have profound effects on health breadth." (PMID 37600699, 2023). "Moreover, PAX8 heterozygous mice exhibit poor performance in functional physical tests and accumulated oxidative damage, indicating that even mild alterations on TH levels (mild hypothyroidism) have profound effects in health span." (PMID 33048427, 2020). "It is therefore tempting to speculate that hypothyroidism in Pax8 +/- mice hinders postnatal beta cell maturation with subsequent increased in the susceptibility to stress-induced apoptosis with age, favouring the replacement of beta cells by delta cells that do not require MafA." (PMID 31518338, 2019). "Mice lacking functional thyroid follicular cells, Pax8−/− mice, die early postnatally, making them suitable models for extreme hypothyroidism." (PMID 35456949, 2022). "These contradictory observations led us to assess the specific effect of the modulation of TH levels in murine healthspan and lifespan using the Pax8 knock-out animal model of hypothyroidism (Wild type [Wt], Pax8 +/- and Pax8 -/-) supplemented or not with THs." (PMID 31518338, 2019). "Knockout mice lacking PAX8 have a smaller thyroid, with normal calcitonin-producing parafollicular C cells but no follicular cells; thus, they suffer from severe hypothyroidism." (PMID 24766781, 2014).
endometrial cancer (19 papers, 2014 to 2026). Primary or metastatic malignant neoplasm involving the endometrium (mucous membrane that lines the endometrial cavity). "While PAX8 loss is more common in high-grade endometrial carcinomas, this case was well-differentiated." (PMID 40959354, 2025). "Recently we also found PAX8 overexpression was associated with the serous subtype of endometrial cancer as well as EC tumor grade, yet unexpectedly, in the present study PAX8 expression was low in MT-ECs compared to pure EC counterparts." (PMID 26132201, 2015). "PAX8 has also been associated with certain endometrial cancers due to its role in cell growth." (PMID 34540435, 2021). "Also, overexpression of PAX8 in endometrial cancer is associated with a poor prognosis." (PMID 24628993, 2014). "ER, PR, PAX8, and P16 expression are commonly used in the pathological examination of endometrial cancer to guide treatment selection." (PMID 40356925, 2025). "In endometrial cancer, PAX8 is expressed in over 90% of tumors of endometrioid and serous histologies." (PMID 35806410, 2022). "We have published on the role of PAX8 in an especially aggressive subtype of endometrial cancer, uterine serous papillary carcinoma." (PMID 35806410, 2022). "We found that the methylation level of the PAX8 promoter region in endometrial cancer tissues was also significantly lower than that in the normal control group in the TCGA database." (PMID 35672291, 2022). "Bisulfate-based amplicon sequencing (BSAS) technique revealed that methylation of the PAX8 promoter region in the two endometrial cancer cells was significantly lower than that in the control cells." (PMID 35672291, 2022). "More studies are needed to test the possibility of using PAX8 as a possible target for managing endometrial carcinomas." (PMID 34540435, 2021). "The role of PAX8 as a treatment target has not been thoroughly studied yet, so more studies are needed to evaluate the potential of targeting PAX8 to treat different PAX8 positive epithelial carcinomas, especially thyroid, ovarian, and endometrial carcinomas." (PMID 34540435, 2021). "In general, PAX8 can be considered a poor prognostic marker in patients with endometrial carcinomas and can be targeted for therapy in selected patients, the utility of which needs more clinical data." (PMID 34540435, 2021). "Considering that urothelial neoplasms are among these occasionally PAX8-positive tumors, PAX8 cannot reliably be used to distinguish urothelial carcinoma from renal cancer in kidney masses or from ovarian or endometrial cancer in pelvic masses as previously suggested." (PMID 39105782, 2024). "So why is PAX8 highly expressed in endometrial cancer cells?" (PMID 35672291, 2022). "DNA methylation can cause gene silencing, so we consider whether the overexpression of PAX8 in endometrial carcinoma may be related to this epigenetic change." (PMID 35672291, 2022). "Therefore, a study on 229 patients was done to find the correlation of PAX8 expression in specific clinical parameters of endometrial cancer." (PMID 34540435, 2021).
endometrial cancer (continued). "Interestingly, a high frequency of PAX-8 expression was noted among females diagnosed with endometrium cancer compared to SCC, this finding is in contrary with a previous report where PAX-8 was expressed among only 3% of the studied samples." (PMID 32847623, 2020). "Therefore, we first knocked down DDX5 in endometrial cancer cells by siRNA, and found that the protein expressions of both c-MYC and PAX8 were reduced." (PMID 35672291, 2022). "PAX8 was found to be positive in 72.1% of 97 patients, 72.7% of 77 endometrial cancer patients, and 72.2% of 18 patients with non-endometrioid cancers." (PMID 34540435, 2021). "This subset of endometrial carcinoma is unusual in that it is immunohistochemically negative for PAX8 and thus cannot be said to show Müllerian differentiation." (PMID 34977100, 2021).